APOB (apolipoprotein B)
Diseases named in the same sentence as APOB in open-access papers (continued):
Sharing a sentence is not in itself a finding about the gene and the disease.
Hypertension (continued). "Additionally, in the hypertension group, TT carriers showed a higher tendency of serum triglyceride (P = 0.069) and significantly higher apolipoprotein B (P = 0.015) and smaller low-density lipoprotein (LDL) particle size (P < 0.001) than either TC or CC subjects." (PMID 29208002, 2017). "Across feature-selection methods, the most influential predictors for CHD included ABSI, prealbumin (PA), direct-to-total bilirubin ratio (DB/TB), apolipoprotein B (ApoB), globulin (GLO), apolipoprotein A-I (ApoA-I), and essential hypertension (EH)." (PMID 41717576, 2026). "There were statistically significant differences betweenthe T2DM and non-T2DM groups in terms of age, non-marital status, educationalattainment, BMI, types of SMD, hypertension, fatty liver, TG, HDL-C, ApoB, and TC(p< 0.001)." (PMID 41209502, 2025). "Significant variations were observed in waist circumference, BMI, ALP, GLU, TG, LDL, ApoA1, ApoB, LDH and vegetables consumption among female hypertension participants." (PMID 39512695, 2024). "And levels of weight, WC, BMI, WHtR, SBP, DBP, TG, TC, LDL-C, ApoB, uric acid, FPG, HbA1c and Hs-CRP were also higher in participants with new-onset hypertension (p < 0.05)." (PMID 38156282, 2023). "Using this algorithm, all hug targets of metformin against obesity-related hypertension were identified accordingly, including IL6, CCL2, Leptin (LEP), Apolipoprotein B (APOB), serine protease inhibitor clade E member 1 (SERPINE1), Apolipoprotein E (APOE)." (PMID 34334083, 2021). "Overweight patients with hypertension had important statistical differences in BMI percentiles, systolic and diastolic pressure, homocysteine, HDL cholesterol, TG, uric acid, ApoA and ApoB compared to the control group." (PMID 34599252, 2021). "As results, the identified findings using network pharmacology analysis had identified total six hug genes of metformin treating obesity/hypertension, including IL6, CCL2, LEP, APOB, SERPINE1, and APOE." (PMID 34334083, 2021). "The risk factors for prediabetes subtypes were considered for sex, age, BMI, central obesity, smoking, drinking, hypertension, lipoprotein ratios (CHOL/HDL, LDL/HDL, TG/HDL and ApoB/A1) and hs-CRP." (PMID 32295016, 2020). "Compared with the normal TG group, the incidence of hypertension in the hypertriglyceridemic group was significantly increased (60.6% vs. 34.8%, P = 0.023), and BMI, TC, LDL-C, VLDL-C, and ApoB showed the same trend." (PMID 33178837, 2020). "A negative correlation of serum TBIL with diabetic duration, PP, TG, ApoB/ApoA, neutrophil and WBC counts, NLR, fibrinogen, urinary ACR, VPT values, and the prevalence of hypertension, DFU, DPN, DN and DR was also observed (P < 0.01 or P < 0.05)." (PMID 31827625, 2019). "The levels of FPG, TC, LDL-C, and the percentages of T2D and hypertension were higher but the concentrations HDL-C, ApoA1 and the ApoA1 to ApoB ratio were lower in persons who suffered from CHD than in controls (P < 0.05)." (PMID 29439709, 2018). "Patients with PDD also suffered less hypertension and had lower serum low-density lipoprotein cholesterol (LDL-C) and apolipoprotein B (Apo-B) levels than the patients with PD." (PMID 30233306, 2018). "Initially, we performed univariate logistic regression analysis to firstevaluate the association of T2DM and 14 variables (age, gender, non-maritalstatus, educational attainment, BMI, type of SMD, hypertension, fatty liver, UA,LDL-C, TG, HDL-C, ApoB, TC) in SMD." (PMID 41209502, 2025). "In this study, based on the data from the China Health and Nutrition Survey database, we utilized the LASSO regression algorithm to distill nine crucial features from a pool of 30 variables, including age, hypertension, TP, triglyceride, BMI, total cholesterol, WBC, apolipoprotein B and HDL_C." (PMID 40140819, 2025).
Hypertension (continued). "Our research indicated that even when accounting for factors such as AF, Hypertension, SBP, Stroke, Type 2 diabetes, Triglycerides, LDL, HDL, apolipoprotein A1 levels, apolipoprotein B levels, and apolipoprotein E levels, migraine continues to elevate the risk of AD." (PMID 38903170, 2024). "Among women, additionally triglycerides, ApoB, insulin, HOMA-IR, ALAT, diastolic blood pressure, hypertension, alcohol intake, and heavy drinking showed a direct association with EAT thickness, while for HDL-C, educational years and annual income inverse associations were observed (Model 1)." (PMID 38796541, 2024). "In our subgroup analyses, higher ApoB levels were correlated with the incidence of CKD in people with non-hypertension, non-hyperuricemic, and non-anemic after adjustment for confounders." (PMID 37124758, 2023). "Parameters up to statistical significance in males or females, for example age, hypertension, LDL-C, ApoB, creatinine, cystatin C (log10) and UA, were incorporated into the stepwise linear regression models to determine which parameters were independently associated with homocysteine." (PMID 37587534, 2023). "In the current study, we have showed that apoB/non-HDL-C was an independent risk factor for nAMD, pachy-nAMD, non-pachy nAMD, and non-pachy PCV, after adjusting for age, sex, duration of hypertension, BMI, and lipoproteins by multivariable logistic analysis." (PMID 35928899, 2022). "In conclusion, NAFLD was strongly associated with impaired anti-inflammatory function of apoB-depleted plasma independent of HDL-C, hypertension, and obesity indices." (PMID 35413066, 2022). "Mean height, SBP, DBP, pulse pressure, TG, the percentages of subjects who consumed alcohol or smoked cigarettes, and the prevalence of hypertension were higher (p ≤ 0.003), whereas mean HDL-C, ApoA1, and the ratio of ApoA1 to ApoB were lower (p ≤ 0.001) in IS than in control groups." (PMID 35559044, 2022). "ApoA1 level was lower but apoB level was higher in women with hypertension than those without hypertension after 8 years." (PMID 36551995, 2022). "Conditional logistic regression analysis revealed that BMI, hypertension, traditional lipid parameters (TC and LDL-C), and non-traditional lipid parameters (nonHDL-C, APOB, APOE, ATH index, AI, CRI-I, CRI-II, and LCI) were risk factors for the onset of SSNHL (Model 1)." (PMID 38714080, 2024). "We therefore selected a sub-group of patients with the 10 highest individual anti-ApoB IgG levels with clinical obesity and hypertension (“high” CVD risk) and with the 10 lowest individual anti-ApoB IgG levels without clinical obesity and hypertension (“low” CVD risk)." (PMID 35479271, 2022). "Compared with females, males had significantly higher age, BMI, SBP, DBP, ALT, AST, ZJU index, Cr, urea, UA, LDL-C, non-HDL-C, TG, ApoB, glucose, HbA1c, and prevalence of hyperglycemia and hypertension, whereas lower eGFR, HDL-C, and ApoA1 levels (all p < 0.001)." (PMID 35770226, 2022). "Patients with carotid plaque had higher plasma TG (1.5 vs. 0.9 mmol/L, p = 0.001), Non-HDL-C (3.5 vs. 3.1 mmol/L, p = 0.025), and apoB concentrations (1.0 vs. 0.9 g/L, p = 0.010) and a higher prevalence of hypertension (80 vs. 37.5%, p = 0.003) than patients without carotid plaque." (PMID 34065555, 2021). "However, marital status, parity, economic level, overweightness, obesity, abdominal obesity, hypertension, family history of cancer, TC, triglyceridemia, TC/HDL-C ratio, ApoA-I, ApoB, ApoA-I/ApoB ratio, SBP, and DBP were significantly associated with HDL-C values." (PMID 34065252, 2021). "In associating the two groups with SNPs, we analyzed their basic demographic information, including age, gender, smoking status, drinking status, and hypertension, and the following variable values, such as CKMB, TC, TG, HDL, LDL, ApoA, ApoB, Glu, Bun and Cre, which may be related to CHD." (PMID 32066403, 2020).
Hypertension (continued). "Levels of LDL-C, non-HDL-C, and apoB were associated with elevated CIMT either in univariate analysis (model 1) or after adjusting for age, sex, history of hypertension and smoking (model 2), or with further adjustment for eGFR, log-transformed levels of hsCRP, HbA1c, and triglyceride (model 3)." (PMID 31019490, 2019). "Among women, the association of marital status with risk of AMI was consistently observed in women with a high or low education level, in those with a high or low income, in those with or without history of hypertension, and in those with a high or low ApoB/ApoA1 ratio." (PMID 22245707, 2012). "We detected that anti-ApoB IgM plasma levels were significantly decreased in patients with T2DM and the MS but were not modulated by smoking status, arterial hypertension (HTN), or obesity." (PMID 35479271, 2022). "The SSNHL group exhibited significantly higher prevalence rate of hypertension and higher levels of body mass index (BMI), TC, LDL-C, nonHDL-C, APOB, APOE, ATH index, AI, CRI-I, CRI-II, and LCI compared to the control group, with statistical significance." (PMID 38714080, 2024). "For those who were not on anti-hypertensive treatment, those with a history of hypertension during pregnancy had lower total and HDL-cholesterol, as well as apolipoprotein B and A1, concentrations than those without such history." (PMID 27529390, 2016). "Furthermore, we used ApoB levels as a surrogate for non-HDL cholesterol and hypertension medication for blood pressure." (PMID 34145379, 2021). "Sex (1 = male, 2 = female), diabetic family history (1 = yes, 0 = no), smoking (1 = smoker, 0 = nonsmoker), hypertension (1 = hypertension, 0 = nonhypertension), BMI, disease duration, HbA1c, 25(OH)D, TC, HDL, TG, LDL, ApoB, ApoA1, and LPA were regarded as covariates." (PMID 33299499, 2020).
Obesity (230 papers, 2006 to 2026). Accumulation of substantial excess body fat. "After stratification for potential pro‐steatogenic risk factors, obesity enhanced the effect of APOB variants on ALT and AST levels." (PMID 41549954, 2026). "In this regard, recent studies reported that higher levels of APOB were a good risk predictor for long-term cardiovascular events in patients with obesity." (PMID 38703299, 2024). "While there is abundant evidence of dysfunctional ApoB signaling in obesity, type 2 diabetes 23–25, and neurodegenerative disorders 26,27, a direct causal link involving ApoB has yet to be investigated." (PMID 39386724, 2024). "In the first step, we assessed the causal effects for TG, LDL-C and ApoB on the five obesity-related phenotypes." (PMID 38863926, 2024). "In this study, a higher risk of obesity was found in older participants (≥ 40 years) with the “AA” genotypes of APOB SNP rs512535 (Pinteraction = 0.004) and tumor necrosis factor (TNFA) SNP rs361525 (Pinteraction = 0.007) with low levels of ME." (PMID 36776603, 2023). "Other studies showed that the cholesterol-deplete apoB is also associated with obesity, blood glucose disorders and cardiovascular diseases." (PMID 35928899, 2022). "After adjustment with obesity indices, the association of anti-inflammatory capacity of apoB-depleted plasma with NAFLD remained significant." (PMID 35413066, 2022). "Elevated apolipoprotein B (apoB-100) is a common abnormality in insulin-resistant subjects with obesity and type 2 diabetes and increases the risk of cardiovascular disease." (PMID 36470666, 2022). "We used a Drosophila model to demonstrate that exercise-training regulates the expression of apoLpp (a homolog of apolipoprotein B) in cardiomyocytes, thereby resisting heart insufficiency and low exercise capacity caused by obesity." (PMID 34305631, 2021). "Genetic defect in MTTP or APOB gene is associated with liver steatosis, obesity, and insulin resistance." (PMID 30037134, 2018). "The precise mechanism connecting APOB with tumorigenesis is unclear, although the biological association between obesity and cancer is already known to be related to circulating lipid levels and tissue lipid metabolism." (PMID 30429453, 2018). "The high C-statistic and retention in the model support prediction of MHO and lower risk attributable to the apoB : apoA-I ratio and support use of the ratio as a measure of cardiovascular risk attributable to obesity." (PMID 28473926, 2017). "What we have observed in the current study is a similar significant impact of another variant of the APOB gene demonstrating an alternate risk of modifying risk of obesity resistance." (PMID 27811965, 2016). "A significant association of apoB XbaI gene polymorphism with obesity and serum lipid levels has been documented, but contradictory results are also available." (PMID 25889118, 2015). "Several apoB restriction fragment length polymorphisms (XbaI, EcoRI, MspI) have been reported to be associated with variation in lipid levels and obesity." (PMID 25889118, 2015). "Only several studies have shown that genetic variants in APOB gene are associated with body size and obesity in children and adults and with body growth and obesity in chicken." (PMID 26451733, 2015). "Several single nucleotide polymorphisms in the apoB gene have been associated with variation in lipid levels and obesity." (PMID 25889118, 2015). "This study investigated the cross-sectional association of obesity, diet and lifestyle factors with apoB/apoA-I and total cholesterol/HDL respectively, in a Swedish population of 2,907 subjects (1,537 women) as part of the INTERGENE study." (PMID 22848405, 2012). "The positive correlation between the apoB/apoA1 ratio and hs-CRP and WBC was observed, so we think that apoB/apoA1 ratio was associated with not only lipid, but also with chronic low grade inflammation caused by obesity." (PMID 23554700, 2011).
Obesity (continued). "This included protein kinase C elipson (PRKCE), known to be involved in brain tumors, carnitine palmitoyltransferase I (CPT1A), 11β-hydroxysteroid dehydrogenase type 1 (HSD11B1) and apolipoprotein B (APOB) which are all linked to obesity." (PMID 20502671, 2010). "It has been demonstrated that polymorphisms of APOB gene are associated in broiler lines with weight gain and obesity." (PMID 19154572, 2009). "In addition, there is a clear causal relationship between the ApoB/ApoA1 ratio and indicators related to glucose metabolism, obesity, and biological behavioral characteristics, serving as a mediating effect in CMD and related risk factor." (PMID 38310324, 2024). "Moreover, increased abundance of this protein in patients with obesity were decreased by bariatric surgery, revealing the role of this intervention in reducing levels of APOB and decreasing risk of cardiometabolic diseases." (PMID 38703299, 2024). "Obesity was positively associated with amino acids (tyrosine, phenylalanine, isoleucine, leucine, and valine), fatty acids, glycoprotein acetyls, apolipoprotein B, and small, medium, and large low-density lipoproteins (LDL) and very low-density lipoproteins (VLDL) measures." (PMID 36118877, 2022). "Conversely, inhibition of apoB can prevent obesity and reduce cardiovascular risk." (PMID 36470666, 2022). "Furthermore, an inverse association between obesity among men and DD, and also between ApoB/ApoA1 ratio and DD was found in both sexes." (PMID 34282190, 2021). "Furthermore, inverse associations with incident DD were found for obesity among men, and ApoB/ApoA1 ratio among both sexes." (PMID 34282190, 2021). "Thus, it is possible that increased PC levels associated with the rs9939609 variant promote T2D and obesity via fat accumulation in the body as well as by inflammation caused by ApoB-induced LDL augmentation in the blood." (PMID 27249024, 2016). "It is possible that some other polymorphism in its vicinity might be present, which is in linkage disequilibrium with apoB XbaI polymorphism and accountable for the observed association with obesity and lipid levels in other studies." (PMID 25889118, 2015). "Obesity associates with both high triglyceride concentration and high apoB/apoA1 ratio." (PMID 25000408, 2014). "Therefore, the association between the ApoB/ApoA1 ratio and obesity, blood pressure, glucose, lipid, and IR parameters confirmed the potential role of the ApoB/ApoA1 ratio in the etiology of metabolic disorders and thus in the occurrence and development of MetS." (PMID 35069437, 2021). "Variants of the apoB gene may therefore be involved in the pathogenesis of obesity." (PMID 25889118, 2015). "Similar to ob/ob mice, DIO mice, which represent a more relevant model for obesity-driven metabolic disease, also displayed increased hepatic protein levels of Grp78 as well as ApoB after treatment with FGF1." (PMID 41541501, 2026). "Mechanistically, hepatic Rab2A inhibition protected mice from high-fat diet–induced obesity and was associated with markedly elevated circulating FGF21, the phenotype largely rescued by adenovirus-mediated knockdown of either CREBH or APOB." (PMID 41314545, 2025). "In this obesity and MetS model, APOB-100 overexpression leads to an increased low-density lipoprotein (LDL)/HDL ratio and a more human-like serum lipid profile in mice." (PMID 40855499, 2025). "Beyond LDL-C control, there is growing recognition of the importance of addressing atherogenic dyslipidemia, characterized by elevated triglyceride and apolipoprotein B levels, especially in the context of increasing obesity and insulin resistance." (PMID 40943795, 2025). "In the obesity trial, at 36 weeks, ApoB decreases observed with orforglipron ranged from − 11.4 to − 13.4%, statistically different from the effect of placebo (− 2.7%)." (PMID 40481478, 2025).